LEP (leptin)
Diseases named in the same sentence as LEP in open-access papers (continued):
Sharing a sentence is not in itself a finding about the gene and the disease.
tumor (continued). "In a patient-derived GBM preclinical model, IL-17A inhibitors increased overall survival and decreased tumor growth/tumor hypoxia, angiogenesis, VEGF expression, cell proliferation, leptin expression and adipogenesis compared to control samples." (PMID 33316976, 2020). "Taken together, these results suggest that leptin and subsequent CTSA downregulation stimulate tumor invasion and metastasis via activation of the EMT process." (PMID 33255835, 2020). "Conversely, the two major adipokines, adiponectin and leptin, as well as some growth factors (EGF, VEGF-α and HGF) seemed to play a major role in the tissue crosstalk around the tumour." (PMID 32472095, 2020). "WCAF treatment decreased the mRNA expression of Leptin and VEGF-A, while the protein levels of CD31, LEP-R, VEGFR-1, STAT3, and p-STAT3 were decreased in tumor tissues." (PMID 33746736, 2020). "At 24 days after injection, CR-fed mice exhibited lower tumor volume concomitant with reduced body weight, body fat, serum IGF-1, leptin, and insulin." (PMID 31906264, 2020). "Aspirin mitigated the increments of glucose, insulin, leptin, WBC, neutrophils, lymphocytes, glutamine, soluble P-selectin, and TGF-β1 in tumor-bearing HFD-fed mice." (PMID 32121098, 2020). "In our study, WCAF treatment decreased the mRNA expression of Leptin and the protein level of LEP-R, in tumor tissues." (PMID 33746736, 2020). "Our findings indicated that ICT can diminish both the tumor formation and mortality of HFD-fed TRAMP mice through reduction of leptin levels and elevation of adiponectin levels." (PMID 33046976, 2020). "Among them, the expression of CNR2, GIP, GNGT1, NPY1R, SSTR5, and LEP in tumor tissue was significantly lower than in normal tissue, while the expression of GPSM2, and NMU was significantly highly expressed in tumor tissue." (PMID 33169793, 2020). "The overall tendencies were matched with mRNA expression, but leptin and knockdown of CTSA significantly upregulated MMP9 (matrix metalloproteinase 9), a biomarker of tumor invasion and metastasis." (PMID 33255835, 2020). "This implies that tumor-bearing in HFD-fed mice tends to decrease body mass, epididymal fat mass, plasma glucose, plasma insulin, plasma leptin, and insulin resistance, while elevating plasma glutamine." (PMID 32121098, 2020). "As a consequence, targeting the FAO/leptin axis led to decreased BCSC numbers, reduced chemoresistance, and reduced tumor growth in vivo." (PMID 33371274, 2020). "Next, to dissect the mechanism of how ERβ can increase the HUVEC tube formation, we focused on tumor angiogenesis-related genes, including Angiogenin, ANGPT-2, bFGF, EGF, HB-EGF, HGF, Leptin, PLGF, and VEGF-A35." (PMID 32409702, 2020). "LEP is found to be involved in the cell cycle, JAK-STAT signaling pathway and apoptosis to regulate tumor growth arrest and apoptosis." (PMID 32528533, 2020). "Binding of leptin to its receptor activates transcription (JAK/STAT) and Ras/extracellular signal-regulated kinase signal transduction pathways, inducing tumor cell proliferation and migration and suppressing apoptosis." (PMID 32596369, 2020). "In vivo, athymic nude mice were transplanted with Hep3B human hepatoma cells, and after leptin administrations, the HCC-harboring athymic nude mice resulted in significant inhibition of the tumor growth and improved survival rates in these animals." (PMID 33316927, 2020). "Tumor weight correlated positively with mouse body weight, liver weight of mice, serum glucose, HOMA-IR, leptin, and visfatin." (PMID 33381605, 2020). "Leptin secreted into BMA binds leptin receptor on the tumour cells, which induces tumour progression." (PMID 31334678, 2019). "Leptin promotes epithelial–mesenchymal transition (EMT), cell migration and invasion in epithelial breast cells, leading to tumor progression." (PMID 31554180, 2019).
tumor (continued). "Given the already established role of LEP/LEPR system in growth promotion, it may be assumed to be causally related to carcinogenesis, where its growth effect may go out of control and result in tumorous growths or its hyperactivity may help the tumor to grow faster." (PMID 31592340, 2019). "ObASCs have been shown to promote tumor growth and metastasis of MCF7 through increased secretion of leptin, which upregulates aromatase and ERα." (PMID 30897853, 2019). "Thus, in the present study, the role of prolonged leptin exposure in tumor progression and/or expansion, as it may occur in vivo in TC patients with high BMIs, was first analyzed in two PTC-derived cell lines carrying RET/PTC1 (TPC-1) and BRAF (K1) mutations which both express OB-R." (PMID 30906321, 2019). "Adipocyte-derived factors, such as leptin, interleukin-6 (IL-6), adiponectin, tumor necrosis factor (TNF-α), monocyte chemotactic protein-1 (MCP-1) and endotrophin (ETP), function within the tumor microenvironment to promote tumor progression." (PMID 30563531, 2018). "The increase in leptin instead in obese patients with PDAC increases the expression of matrix metalloproteases, especially MMP-13, with the acquisition of a more invasive tumor phenotype." (PMID 30366466, 2018). "Inhibition of leptin (by IONP-LPrA2) after subcutaneous implantation of PC cells delayed tumor onset and decreased tumor size as well as cancer stem cell markers." (PMID 30567565, 2018). "In conclusion, present data strongly suggest that leptin is an important factor involved in PC proliferation and tumor growth, expansion of PCSC populations, which are related to leptin-induced upstream activation of Notch pathway." (PMID 27999190, 2017). "In 87% of cases, the proteins belonged to pathways related to local tumor progression, metastasis and/or angiogenesis (i.e. cathepsin D, MMP-9, eNOS, Leptin, ANGPTL4, autotaxin)." (PMID 29245929, 2017). "This is the first evidence to demonstrate the relationship between two proteins present in the tumor microenvironment, leptin and sPLA2-IIA, and the effect of this tandem on tumor progression." (PMID 28249041, 2017). "For example, increased leptin expression has been found in HCC cell lines and HCC tissue, as well as to increase tumor invasiveness and the migration of HCC." (PMID 28178643, 2017). "The pivotal roles of estrogen receptor signaling in leptin-induced cell cycle progression, apoptosis suppression, and autophagy induction were further confirmed in MCF-7 tumor xenograft model." (PMID 29312618, 2017). "Excess adipose tissue leads to increased secretion of IGF-1, IL6, leptin and TGF-α which can promote tumor growth." (PMID 28768896, 2017). "Moreover, it has been reported that leptin is able to regulate and activate several signaling pathways and oncogenes which are critically implicated in BCSCs and leptin deficiency in MMTV-Wnt-1 transgenic mice results in functional depletion of BCSCs leading to less tumor outgrowth." (PMID 26556856, 2016). "Leptin also induces crosstalk with Notch and IL-1 (NILCO), which involves other angiogenic factors promoting tumor growth." (PMID 27472371, 2016). "Altered secretion profile of leptin, and adiponectin, and other inflammatory adipokines such as IL-6 and TNF-α, by interacting with signaling network, accelerate neoplasia." (PMID 27980732, 2016). "The findings have shown that protein which includes the likes of Eotaxin, Fas ligand, IGF-II, IL-1β, TNF-α, IL-13, Leptin, and TIMP-1 were decreased when compared to the untreated tumor." (PMID 27558166, 2016). "Tumor status induced a significant decrease in the expression of FIGF (P < 0.0001), ADIPOQ (P < 0.0001), LEP (P = 0.0009), PTHLH (P = 0.0345) and FOS-like Antigen 1 (FOSL1; P < 0.0001) compared with expression in corresponding non-tumor tissue." (PMID 27857161, 2016).
tumor (continued). "Therefore, we plan to investigate whether administering a mixture of leptin inhibitor together with a CCL2 inhibitor to tumor bearers will result in a better approach to reduce tumor progression and adipose tissue inflammation in this tumor model with DIO mice." (PMID 25599228, 2015). "Only in postmenopausal subgroups, leptin, resistin, and visfatin levels were positively correlated with TNM staging, tumor size, lymph node (LN) metastasis, and histological grading." (PMID 25838618, 2015). "Leptin expression can be up-regulated through hypoxia-inducible factor-1(HIF-1) alpha, which controls tumor angiogenesis in many solid tumors." (PMID 26147886, 2015). "Leptin levels were positively correlated with TNM, tumor size, LN metastasis, and histological grading (r = 0.338, P = 0.038; r = 0.241, P = 0.029; r = −0.820, P = 0.000; and r = −0.762, P = 0.000)." (PMID 25838618, 2015). "More specifically, when evaluating score alone AdipoR1, adiponectin, Ob-R, leptin, COX-2, F2-isoprostanes, PGF2α and α-SMA were also higher in the tissues adjacent to the tumor compared to the tumor tissues." (PMID 26431176, 2015). "The PANC-1-Leptin and the control PANC-1-Lv cells were then inoculated subcutaneously into nude mice, and the tumor growth was monitored once per week." (PMID 25948792, 2015). "Leptin treatment also showed increase in MMP-9 expression in hepatic cancer cells and endothelial cells to induce invasion of tumor cells." (PMID 25704884, 2015). "The aim of the present review is to address the role of ghrelin, myostatin, leptin, HIF, IL-6, TNF-α, and ANGPTL-4 in the regulation of energy balance, tumour development, and tumoural cell invasion." (PMID 26508818, 2015). "We utilized tumor tissue samples from the same experiment to examine the effect of HNK treatment on the expression and activation of important leptin-signaling molecules." (PMID 26036628, 2015). "Therefore the overall impact of 2.17-mAlb on tumor growth was determined not only by the direct effects of LepR antagonist on tumor cells and/or other cells supporting tumor growth, but also by other systemic factors such as insulin metabolism that are regulated by leptin." (PMID 24587106, 2014). "The inflammatory response-related genes (CCL14 (−4.52), LEP (−3.73) and PTGDS (−3.84)) showed decreased expression in the recurrence tumor tissues." (PMID 24377043, 2013). "Leptin has also been shown to stimulate angiogenesis and activate insulin-like growth factor 1 (IFG-1), resulting in increased tumor invasion and metastasis." (PMID 23050155, 2012). "Our previous work demonstrated that leptin and ObR are significantly overexpressed in human GBM tissues and the presence of both biomarkers correlates with tumor grade." (PMID 21771332, 2011). "In addition, leptin might also contribute to tumor neoangiogenesis." (PMID 21771332, 2011). "Other investigators have shown that leptin indirectly transactivates erbB2 and stimulates epidermal growth factor (EGF) receptor phosphorylation in tumor cells." (PMID 21533119, 2011). "Therefore, it is possible that high levels of leptin found in the tumour microenvironment, derived either from tumour or adipose cells, can upregulate the expression of Ob-R by tumour cells leading to the increase of tumour growth and expression of pro-angiogenic and inflammatory factors." (PMID 21139583, 2011). "Mouse tumor stroma in ER+ BC expressed high levels of VEGF and leptin that was induced by leptin signaling." (PMID 19531256, 2009). "Leptin engages proliferative, anti-apoptotic, and migratory signalling via PI3K–Akt and JAK2–STAT3 cascades, thereby supporting cellular survival within the tumour microenvironment." (PMID 41586225, 2025). "For example, leptin produced by adipocytes upregulates enzymes involved in FAO by activating the transcription factor STAT3, which inhibits the glycolysis of CD8+T effector cells and impair their anti-tumor effects." (PMID 40290117, 2025).
tumor (continued). "Although leptin produced by local adipose tissue near the tumour does not affect proliferation, it reduces cell adhesion and enhances the migration and invasiveness of renal epithelial cells." (PMID 40790491, 2025). "Leptin enhances cancer cell colonization, autophagy, and chemoresistance by activating the JAK2/STAT3 and RAS signaling pathways, creating a feedback loop that further supports tumor survival." (PMID 40852589, 2025). "Moreover, leptin exacerbates the TME by increasing the secretion of proinflammatory cytokines, thereby enhancing tumor cell invasion and metastasis." (PMID 41267926, 2025). "Additionally, leptin exposure in human NK cells also upregulated CD69, boosted IFN-γ secretion, and strengthened tumor cell conjugate formation, partly through increased expression of tumor necrosis factor-related apoptosis-inducing ligand (TRAIL)." (PMID 41516046, 2025). "Conversely, leptin and resistin, which are pro-inflammatory adipokines, contribute to tumour-promoting processes by activating the PI3K/Akt/mTOR signalling pathway, thereby sustaining tumour cell survival, growth, and invasion." (PMID 41002741, 2025). "In particular, the negative expression of Leptin helps differentiate tumor cells from normal adipose tissue, indicating a deviation from normal adipose differentiation pathways." (PMID 39591300, 2024). "Leptin can regulate other factors and pathways affecting bone resorption, such as matrix MMP2 and MMP9, which are involved in extracellular matrix remodeling, tumor progression, and bone absorption." (PMID 38571500, 2024). "Immunohistochemical analysis demonstrated the positive expression of S100A4, CDK4, MDM2, CD34, and Vimentin, along with the negative expression of Leptin, confirming the tumor’s high aggressiveness and malignancy." (PMID 39591300, 2024). "Leptin-stimulated production of soluble ICAM-1, in coordination with RANKL activation, synergistically induces OC formation, suggesting that leptin indirectly promotes tumor-induced bone resorption." (PMID 38571500, 2024). "The expression of LEP and LEPR did not showed association with menopausal status, histological type, tumor size, tumor grade and metastasis status (P > 0.05), as well as the expression of ER, PR (P > 0.05)." (PMID 36941557, 2023). "Another study showed that ectopic IL-8 expression in tumor-adjacent adipocytes converted adipocytes into CAAs, with high levels of NF-κB and NF-κB targets (leptin/IL-8/IL-1 and an active pre-oncogenic STAT3-dependent EMT phenotype), on BCCs and in orthotopic tumor xenografts in mice." (PMID 36880535, 2023). "BMI was also significantly correlated with the expression of leptin and macrophage scavenger receptor, and with macrophage pathway expression levels in adjacent normal tissue but not in tumours." (PMID 37173907, 2023). "The authors concluded that high leptin levels do not inhibit tumor cell division at the G2/M stage by blocking the inhibitory effect." (PMID 37190027, 2023). "Mean leptin levels were not different between the groups also tumor tissues had higher strongly positive Ob-R staining however insignificant." (PMID 37942199, 2023). "Therefore, the current study was done to evaluate the serum leptin concentration in GBC patients and its correlation with staging and tumour markers." (PMID 37378223, 2023). "In mechanism, leptin’s interaction with its receptor also enables the activation of the MAPK-ERK, PI3K-AKT, and JAK-STAT pathways, which contributes to malignant traits of tumor cells, such as proliferation, transformation, survival, and self-renewal." (PMID 37509115, 2023). "The reports to date indicate that leptin is overexpressed in FMC, with the highest in luminal B and triple-negative tumors, and lower in circulation, which supports the idea that leptin is recruited into cancerous mammary tissue to facilitate tumor growth." (PMID 37626804, 2023).
tumor (continued). "In both patient categories, IL8 and LEP were up-regulated in tumour tissue: in patients without DMI, 5.8-fold and 5.4-fold, respectively, and in patients with absent LVI, 5.5-fold and 5.0-fold, respectively." (PMID 37509322, 2023). "In addition, studies have reported the relationship between Leptin and the AMPK signaling pathway, where Leptin can activate the AMPK signaling pathway and promote tumor occurrence and progression." (PMID 37542585, 2023). "(H) Tumor weight of E11-KO tumors with or without knockdown of Leptin or p73γ (*p<0.05 by Student’s t-test)." (PMID 37650871, 2023). "Turning to the source of elevated leptin, we first considered direct delivery from local fat, but saw no overt signs of increased adipogenesis in the tumour microenvironment as judged by Oil red O staining." (PMID 36450983, 2022). "Moreover, LEP and RETN affect tumor progression by promoting anti-apoptotic and angiogenic factors as well as production of pro-inflammatory cytokines." (PMID 36362348, 2022). "Tumor growth correlated with serum glucose (p < 0.01), leptin (p < 0.01), and ghrelin levels (p < 0.01), but not with serum insulin levels." (PMID 35361802, 2022). "In this study, we found that patients with NPC had higher levels of leptin in serum compared to that of healthy groups and had elevated leptin in the tumor compared to adjacent non-tumor tissues." (PMID 35778755, 2022). "Overall, with this bidimensional analysis we could show that tumor samples were well characterized by high secretions of IL-16, HGF, the TGF-β1, 2 and 3, SCF, FGF-2 and VEGF, and low secretions of CCL8 and Leptin." (PMID 36539890, 2022). "The CRC microenvironment is related to LEP and LEPR expression, with significantly higher leptin levels in patients, indicating the potential of this molecular autocrine/paracrine signaling loop to interfere with tumor progression processes." (PMID 35563103, 2022). "Leptin can reprogram metabolism through increasing FAO and OXPHOS, and it also promotes mitochondrial biogenesis, inducing differentiation of T cells into memory-like phenotypes which is critical to generate efficient anti-tumor effects." (PMID 35062950, 2022). "Numerous studies have indicated leptin, IL-6, and TNF-α could enhance the metastatic properties of tumor cells by activating of NF-KB or STAT3 signal pathway." (PMID 36361525, 2022). "Previous studies have demonstrated that some of the proinflammatory cytokines, such as leptin, IL-6, and TNF-α, in the tumor microenvironment could promote tumor progression." (PMID 36361525, 2022). "However, PNETs are known to be a particularly metabolically active tumor type, and our analysis indicated that MK2 affects macrophage-dependent production of metabolic factors such as insulin, leptin and resistin in PNETs." (PMID 36362348, 2022). "ASCs from obese mice increase tumor microenvironment leptin levels, directly promoting metastasis rather than enhancing primary tumor growth." (PMID 33815289, 2021). "The immunostaining analysis of the tumor and normal tissue samples revealed that luminal B and triple-negative mammary carcinoma subtypes (p < 0.05) showed leptin overexpression." (PMID 33644151, 2021). "In line with our findings, the authors did not establish any correlations between LEP expression and age, tumor grade, and BMI (p > 0.05)." (PMID 34884678, 2021). "Leptin signaling enriches breast CSCs by increasing receptor expression levels and activating Notch and Wnt stem cell pathways as well as oncogenic HER2, AKT and NF-κB pathways to promote tumor formation and invasion." (PMID 34202411, 2021). "In consistent with the in vitro data, leptin increased FFA level and induced lipid accumulation in tumor tissues, both of which were almost completely suppressed by cotreatment with 3‐MA, confirming the crucial role of autophagy induction in lipid metabolic reprogramming by leptin." (PMID 33226729, 2021).